CD4 (CD4 molecule)
Diseases named in the same sentence as CD4 in open-access papers (continued):
Sharing a sentence is not in itself a finding about the gene and the disease.
lymphoma (continued). "The median CD4 T cell count (Normal rang 550-1440×10^6/L) at lymphoma diagnosis was 110 × 10^6/L (range, 24-434 × 10^6/L), with five cases having CD4 T cell counts <50 × 10^6/L." (PMID 40969752, 2025). "EBNA1 is the predominant EBV-latent antigen for CD4+ T-cells and can be identified by CD4+ T-cells following endogenous MHC class II processing in EBV-positive lymphoma cells." (PMID 40422248, 2025). "Patients with severe immunosuppression, indicated by nadir CD4 counts below 50 cells/mm3, more frequently present with advanced-stage lymphomas (stages III/IV) and systemic symptoms, complicating management and worsening outcomes." (PMID 40606992, 2025). "Conversely, lymphoma patients also showed a higher percentage of differentiated T cells, particularly CD4 EM and CD8 + EMRA cells." (PMID 40630518, 2025). "Here, we show that lymphoma samples contain cytotoxic CD4+ T cells, which were predominantly NKG7/TIA-1+GZMK+ TFH-like in FL and TIA-1+GZMK+ and/or GZMB+ within the CXCR5+PD-1+ and CXCR5–PD-1+ subpopulations of DLBCL." (PMID 41030456, 2025). "An upregulation expression of CTLA-4 on CD4+ T cells was found in the peripheral blood of dogs with B-cell high-grade lymphoma and was related with a poor prognosis." (PMID 39943162, 2025). "Isogenic experiments showed that LY9 KO in CD4+ αβ T lymphocytes and HuT78 T-lymphoma cells impaired the upregulation of T-bet and RORγT induced by polyclonal stimuli or coculture with Raji B lymphoma cells (with or without LY9 KO) plus blinatumomab." (PMID 40446017, 2025). "Lymphoma screening via flow cytometry at Xiangya Hospital revealed a CD4/CD8 ratio inversion (0.6), indicating that the patient had partial immunosuppression and impaired pathogen clearance capacity." (PMID 40963618, 2025). "While both CD4+ and CD8+ T-cells contributed to TIS lymphoma elimination, we found CD4+ T-cells significantly more potent than CD8+ T-cells." (PMID 40159497, 2025). "Following lytic replication, MDV establishes a latent infection in CD4+ T-cells, and only a few infected cells are subsequently transformed, resulting in lethal lymphoma development." (PMID 40430752, 2025). "CD4+ T cells, by activating other immune cells in the TME, are associated with a favorable prognosis in lymphoma." (PMID 40589747, 2025). "Among these 25 lymphoma patients, 23 and 21 had detectable CD4 + and CD8 + memory T cell responses, respectively." (PMID 40630518, 2025). "Compared with the control group, intratumor infiltration of CD4+ T cells and TAMs in mouse lymphoma tumors showed an increasing trend." (PMID 39920772, 2025). "Lymphomas in which B cells avoided PD-1+ T cells had a higher proportion of B cells, as well as PD-1+ CD4+ T cells and PD-1+ CD8+ T cells (adj." (PMID 40772779, 2025). "Cytological analysis of the ascitic fluid revealed numerous lymphomatous cells, leading to a diagnosis of CD4−/CD8+ adult T-cell leukemia/lymphoma." (PMID 40184104, 2025). "In one study, 10.0% of cases of B-lymphoblastic leukemia/lymphoma expressed one or more T cell antigens: CD4 in 5.0% of cases, CD5 in 2.2% of cases, CD7 in 2.2% of cases, and CD2 in 0.6% of cases." (PMID 40227608, 2025). "The average CD4 count during the diagnosis of lymphoma was 95.22 ± 50.61, ranging from 15 to 172/mm3." (PMID 40606992, 2025). "Conversely, HLA-ABC–positive lymphomas consisted of a larger proportion of the CD4+ T cell–rich RCN3 and PD-1+ cell–rich RCN4 (adj." (PMID 40772779, 2025). "Most T-cell lymphomas are CD4+/CD45+ high-grade lymphomas (lymphoblastic or peripheral T-cell lymphomas) expressing low II MHC with an aggressive disease course, regardless of the treatment regimen (median survival of 159 days)." (PMID 39943162, 2025). "Following lytic replication, MDV establishes a latent infection in CD4+ T cells, while a few of these cells are subsequently transformed, resulting in lethal lymphomas." (PMID 41013577, 2025).
lymphoma (continued). "In clinical practice, it is recommended to strengthen lymphoma screening for PLWH with a persistently inverted CD4/CD8 ratio and to incorporate emerging prognostic models into therapeutic decision-making and follow-up monitoring." (PMID 40723865, 2025). "In the analysis of LME, we found that lymphomas with elevated PCDI scores were associated with a diminished presence of immune cells that combat tumours, such as M1 macrophage, CD4+ T cells, and CD8+ T cells." (PMID 39731274, 2025). "Selinexor treatment of mouse models of leukemia and lymphoma reduced the ability of MDSCs to suppress proliferation of CD4+ and CD8+ T cells." (PMID 40565816, 2025). "Conversely, higher CD4 counts at lymphoma diagnosis correlate with better chemotherapy tolerance and longer survival, as observed in our cohort." (PMID 40606992, 2025). "The same patient also showed marked neurotoxicity and progression of the SNCSL despite continuous surface expression of CD19 on the lymphoma cells and an accumulation of CD4+ central memory-type CAR-T cells in the CNS." (PMID 38349430, 2024). "The anti-CD4CAR expression led to expansion of the CD8 TILs in the mAITL lymphoma, while the CD4 neoplastic Tfh-like cells were almost completely eliminated as compared to incubation with GFP encoding CD8-LVs or no vector." (PMID 39272178, 2024). "CD4+ cells exhibited similar abundance, whereas their distribution became progressively more disseminated across the mutant lymphomas." (PMID 38570506, 2024). "This is substantiated when examining individuals clinically diagnosed with AIDS, who exhibit a low count of CD4+ T lymphocytes, leading to high EBV loads and a predisposition to developing neoplasms such as lymphomas." (PMID 39066175, 2024). "Patients with FL are considered at risk of severe infection after rituximab treatment, where CD4-positive lymphocyte counts are usually decreased by lymphoma recurrence, similar to the present case." (PMID 39552980, 2024). "The expression of Tax can induce the immortalization of primary human CD4+ lymphocytes and the transformation of murine fibroblasts, and the transgenic mice of Tax develop lymphoma and leukemia." (PMID 38690287, 2024). "In lymphoma biopsy samples, Treg cells are abundant and have been shown to suppress antitumor immunity by inhibiting other intratumoral CD4+ and CD8+ T-cell populations." (PMID 39020411, 2024). "Human T-cell leukemia virus type 1 (HTLV-1), the first identified human retrovirus in the 1980s, is associated with the development of adult T-cell leukemia/lymphoma (ATL), a highly aggressive malignancy of CD4+ T lymphocytes." (PMID 38690287, 2024). "Mice harboring IRF8 mutant lymphomas displayed higher tumor burden and remodeling of the tumor microenvironment, typified by depletion of CD4, CD8, and natural killer cells, increase in regulatory T cells and T follicular helper cells." (PMID 38996030, 2024). "The median CD4 + T cell count at lymphoma diagnosis was 110 × 10^6 /L (range, 24–434 × 10^6 /L), with 5 cases having counts < 50 × 10^6 /L." (PMID 38622727, 2024). "In our study, the observed expansion of TCRαβ and the increase of CD4+ T cells at 20 and 30 days can be explained by the development of lymphomas." (PMID 39066253, 2024). "In contrast, αCD20-EndoP125A-treated mice demonstrated significantly reduced infiltration of hCD20+ lymphoma cells, and significantly increased CD4+ and CD8+ T cell infiltration within the TDLNs." (PMID 39594584, 2024). "In the E.G7-OVA lymphoma model, vaccination efficiently increases the CD4+, CD8+, and tetramer+CD8+ T cell populations in the spleens." (PMID 38932378, 2024). "MD is characterized by paralysis, immune suppression, and the rapid formation of T-cell (primarily CD4+) lymphomas." (PMID 39861844, 2024). "At lymphoma diagnosis, CD4 count was <200 cells/mm3 in 16 patients (59.2%), 200–350 cells/mm3 in six patients (22.2%) and >350 cells/mm3 in five patients (18.5%)." (PMID 38406522, 2024).
lymphoma (continued). "Despite substantial SHIV-mediated CD4+ T cell depletion and successful RhLCV infection, only 1 of 4 rhesus macaques (25%) developed lymphoma." (PMID 39527641, 2024). "In contrast, the CD4+ subset of the T zone lymphoma (n = 158 cells) was more diverse with the most dominant clone accounting for only 19.6%." (PMID 38649520, 2024). "In mice, the IRF8-mutant driven remodeling of the lymphoma microenvironment was diverse but consistently reflected a procancer profile (decrease in CD4, CD8, NK, and TFH1 and increase in Tregs and TFH cells)." (PMID 38996030, 2024). "The anti-CD4CAR LVs in the current study recognized specifically CD8 as target receptor and allowed the generation of CD4-directed CAR CD8 T cells in vivo, which eliminated CD4 + malignant T cells in a primary murine AITL lymphoma." (PMID 39272178, 2024). "To distinguish between these two activities of the inhibitor, we treated murine lymphoma cells with increasing doses of etomoxir and determined the CD4 + PD1high cell death 3 days after treatment." (PMID 38321568, 2024). "TGF-β produced by lymphoma cells can stimulate the expression of FoxP3, a specific marker for Tregs, which can result in the conversion of CD4 + /CD25- T cells into Tregs." (PMID 39020411, 2024). "Integrating proteomic and metabolomic data obtained from mAITL lymphoma CD4 + PD1high T cells and wild-type (WT) CD4 + cells, allowed us to identify a specific lipid metabolic pathway involved." (PMID 38321568, 2024). "Samples analysed by flow cytometry from peripheral blood and lymph nodes in dogs with B-cell high-grade lymphoma showed higher PD-1 expression in CD4+ and CD8+ T cells than those in clinically healthy dogs." (PMID 38893123, 2024). "Several mice had increases in CD4 counts over time even with depletion, which was suggestive of the development of lymphoma." (PMID 39339897, 2024). "Malignant CD4 Tfh cells were eliminated from the mAITL lymphoma, while the CAR + CD8 T cells expanded upon encounter with the CD4 receptor and were shaped into functional cytotoxic cells." (PMID 39272178, 2024). "In vitro the generated anti-CD4 CAR CD8 T cells were able to eliminate the CD4 T cells in WT C57BL/6 splenocytes as well as in mAITL lymphoma biopsies." (PMID 39272178, 2024). "Our approach assured specific transduction of CD8 T cells resulting in high level anti-CD4 CAR expression by the CD8 T cells present in lymphoma biopsies of a preclinical mAITL mouse model." (PMID 39272178, 2024). "At the time of the initial lymphoma diagnosis, the median CD4+ T count was 182 cells/μL (IQR 92–304)." (PMID 38613207, 2024). "T‐cell lymphomas, especially mycosis fungoides/Sezary syndrome (MF/SS) and adult T‐cell leukemia/lymphoma, sometimes display a CD4+CD26− immunophenotype." (PMID 39235202, 2024). "The expression of TIM3 in lymphoma-derived ECs facilitates lymphoma development and spread by interfering with circulating T cells and inhibiting CD4+ T-cells activation." (PMID 37666809, 2023). "Ex vivo experiments have shown that CD4CAR NK-92 cells possess potent anti-tumor cytotoxicity against various adult and pediatric CD4+ lymphoma/leukemia cell lines, as well as primary CD4+ T-cell malignancies from both adult and pediatric patients." (PMID 37711206, 2023). "H9/NL4-3 cells are a CD4+ lymphoma cell line persistently infected with HIV, with virtually all cells expressing Env on the cell surface and secreting infectious HIV." (PMID 37112741, 2023). "The proximity of CD4+ T cells to lymphoma B cells supports the importance of T cells in regulating the malignant cells." (PMID 37591873, 2023). "Subsequently, a CD4+ T-cell leukemia and lymphoma develops, which leads to eventual death of the mice." (PMID 36819050, 2023). "These clusters all came from CD4+ cells and were highly represented in patients with lower grade lymphomas (ii)." (PMID 37591873, 2023).
lymphoma (continued). "The expression of TIM3 in lymphoma-derived ECs contributes to the onset, development, and dissemination of lymphoma by inhibiting CD4+ T-cell activation, as well as Th1 polarization." (PMID 37666809, 2023). "We report the case of a patient who was referred to our institution with a diagnosis of CD4+ small/medium-sized pleomorphic lymphoma." (PMID 36831170, 2023). "MDV is reactivated preferentially in CD4+ T cells at the second cytolytic infection phase (14–28 dpi), and MDV-infected CD4+ T cells are transformed to lymphoma cells, which proliferate and form solid tumors in various organs." (PMID 36851499, 2023). "These mice develop T cell leukemia and lymphoma, with the major phenotype of leukemic cells being mature CD4+ or CD8+ T cells." (PMID 37511495, 2023). "The decrease in peripheral blood leukocyte and lymphocyte levels prevents patients with lymphoma from rapidly clearing the new coronavirus infection, similar to the general population, through CD4/CD8 and other mechanisms." (PMID 37860581, 2023). "mRNA sequencing in adult T cell leukemia/lymphoma, cutaneous cytotoxic T cell lymphoma, and CD4+ primary human T cells has revealed a third transcript (transcript 3) not reported in Ensembl, encoding a 1399-amino acid protein with 39 exons (isoform 3)." (PMID 36515678, 2023). "In contrast, 12/26 Mnt+/+MYC10hom and 7/24 Mnt+/+MYC10hom/Rag1Cre control mice developed massive thymi (up to 1440 mg) and 14/15 of those immunophenotyped were CD4+CD8+ T lymphomas (the other being a CD19+ B lymphoma)." (PMID 36755068, 2023). "Older children generally have higher death rates, mostly due to advanced-stage disease, poor performance status (PS), and lower CD4+ T-cell counts at lymphoma diagnosis." (PMID 37190220, 2023). "Seven selenoproteins, that included TXNRD1, GPX1, GPX4, SELENOH, SELENOO, SELENOS and SELENOT, were detected in both lymphoma-derived and primary CD4 T cells." (PMID 35163318, 2022). "In similar studies, mouse CD4+ CTLs induced by LMP1-expressing lymphoma cells revealed high Eomes expression whose knockout diminished the cytotoxicity of the CD4+ T cells." (PMID 36077655, 2022). "Patients’ demographics and characteristics by CD4/CD8 ratio stratification at diagnosis of AIDS-related lymphoma (n = 138)." (PMID 35873145, 2022). "Since we observed a significant skewing of the CD8+:CD4+ T-cell ratio during reconstitution, we separately analyzed the impact of the metabolic profile of CD8+ and CD4+ T-cells on the clinical outcome of lymphoma patients." (PMID 35794135, 2022). "Median CD4+ T‐cell count at diagnosis was 191/μl (range, 4–1022), 84 patients (97.7%) were on combination antiretroviral therapy (cART) at lymphoma diagnosis." (PMID 36056692, 2022). "In summary, the CD4/CD8 ratio was a validated independent prognostic parameter in AIDS-related lymphoma among all the patient characteristics analyzed in our study." (PMID 35873145, 2022). "From an immunohistochemical perspective, the primary cutaneous CD4+ small to medium T-cell lymphoma is a rare lymphoma (2% of all cutaneous T-cell lymphomas)." (PMID 36363575, 2022). "The origin of the mouse transplantable lymphoma was therefore of mature CD4+ T‐helper cell origin, reflecting a PTCL." (PMID 35510955, 2022). "Prospective, large samples and multi-center study was needed to further explore the relationship between CD4 count and malignant lymphoma in HIV-infected patients." (PMID 35896979, 2022). "Human T cell leukemia virus type 1 (HTLV-1) mainly infects CD4+ T cells and induces chronic, persistent infection in infected individuals, with some developing adult T cell leukemia/lymphoma (ATL)." (PMID 36185204, 2022). "This study was carried out in an EBV-seropositive patient who, after chemotherapy and allo-SCT for a CD4+ AITL, suffered from relapse and simultaneous increase of peripheral blood EBV load, most likely associated with the leukemic relapse of the lymphoma." (PMID 35452490, 2022).
lymphoma (continued). "The tumor microenvironment plays a vital role in the tumorigenesis and development of DLBCL, and activated memory CD4+ T cells are an essential component of immunological cells in the lymphoma microenvironment." (PMID 35711924, 2022). "The resulting third-party HSC-iNKT (3rdHSC-iNKT) cells closely resembled peripheral blood-derived endogenous CD4− iNKT cells and displayed anti-GvHD activity while preserving GvL effects in preclinical models of leukemia and lymphoma." (PMID 36034226, 2022). "In this study, the superior role of CD4+ T cells compared to cytotoxic CD8+ T cells in the elimination of lymphoma cells was demonstrated." (PMID 36077655, 2022). "Median CD4 T-cell count for PLWH at lymphoma diagnosis was 142 cells/μL (IQR 82–284) pre-UART and 156 cells/μL (IQR 96–273) post-UART (p = 0.54)." (PMID 36048901, 2022). "Skin biopsy before therapy revealed intensive CD4+ lymphoma cell infiltrates, which showed significant improvement 28 days post-infusion." (PMID 36172388, 2022). "The continued attack on CD4+ T lymphocytes by HIV leads to a continuous decrease in the number of CD4+ T lymphocytes, which increases the risk of malignancies, most commonly HIV-associated lymphoma." (PMID 36438738, 2022). "The AP-1 motif was associated with cis-regulatory features of upregulated genes in lymphoma cells versus naive CD4+ T cells and downregulated genes in lymphoma cells versus FYNG2A-TRAF3IP2-expressing CD4+ T cells." (PMID 34140493, 2021). "MD lymphomas are typically composed of transformed, MDV+ CD4+ T lymphocytes and other host cells that have infiltrated the lymphoma tissue." (PMID 34681024, 2021). "A similar association between CREBBP inactivation and reduced expression of MHC class II is observed in murine lymphoma models which alters mutant GC cells ability to present antigen to CD4+ cells." (PMID 34335584, 2021). "The restoration of miR-126 in CD4+ T lymphoma cell lines was shown to significantly reduce cell proliferation compared with the tested controls." (PMID 34205549, 2021). "The median count of CD4+ lymphoma cells was of 604 × 106/L, being ≥1000/μl in 5 cases (B2) (18.5%), corresponding to patients with SS." (PMID 34335777, 2021). "This correlative data highlights the potential cytotoxic anti-tumor capability of specific CD4+ T cell subsets that is relevant for both solid cancers and lymphomas." (PMID 33842331, 2021). "A strategy was developed to conditionally overexpress miR-126 and control miRNAs in transformed CD4+ T cells propagated from Marek’s disease (MD) lymphoma." (PMID 34205549, 2021). "In our current study, we chose CD4-targeting CAR transgenes because CD4+ leukemia and lymphoma are highly aggressive types of tumors that are extremely refractory to chemotherapy." (PMID 34162832, 2021). "By histological analysis many of them were identified as histiocytic lymphomas or high-grade lymphomas with frequent double staining for CD4 and B-cell markers as well as some high-grade sarcomas including osteosarcoma and rhabdomyosarcoma." (PMID 34736527, 2021). "RASGRP1-deficient patients commonly show recurrent infections, inverted CD4+: CD8+ T cell ratio, poor T cell proliferation, defective NK cell function, autoimmunity, and EBV-associated lymphoma." (PMID 34638238, 2021). "TIA-1 is expressed in most CD4− cases, both CD8− and CD8+ (75% and 83%, respectively), and in three out of four tested cases with subsequent transformation to high-grade lymphoma (the three of them being CD4−/CD8+)." (PMID 34205136, 2021). "This lymphoma usually affects PLWH at advanced stages of immunosuppression, with very low CD4+ lymphocyte counts (median < 50 cells/μL) and with loss of immune response mediated by CTLs." (PMID 34771697, 2021). "In that case, T cell lymphoma developed after 20 months of treatment using pembrolizumab, and lymphoma cells expressed CD4+ CD8+, with a slight predominance of CD8+ cells." (PMID 33939308, 2021).